EPCAM (epithelial cell adhesion molecule)
Diseases named in the same sentence as EPCAM in open-access papers (continued):
Sharing a sentence is not in itself a finding about the gene and the disease.
tumor (continued). "Enrichment of rare circulating tumor cells (CTCs) in blood is typically achieved using antibodies to epithelial cell adhesion molecule (EpCAM), with detection using cytokeratin (CK) antibodies." (PMID 21577258, 2011). "Recently, a trifunctional anti-EpCAM antibody (Catumaxomab) has received approval by the European Commission for the treatment of patients with EpCAM positive tumours." (PMID 21281469, 2011). "Following enzymatic digestion, tumor specimens were comprised of EpCAM+ tumors cells, and a CD45+ leukocyte population that contained CD14+ monocytes and CD3+ T cells, as well as a CD14- CD3- leukocyte subset." (PMID 21827675, 2011). "Several cell surface markers, including CD24, CD44, CD133, CD166, EpCAM, or dye efflux assays have been used to sort populations of putative cancer stem cells from primary tumor cultures or cell suspensions obtained from tumor biopsies." (PMID 21264259, 2011). "Knowledge on the role of EpCAM in the process of carcinogenesis, tumour progression and metastasis needs further elucidation." (PMID 21281469, 2011). "Fluorescence activated single cell sorting evidenced a statistically higher clonogenic potential of EpCAM positive tumour cells only in hcc-1 cell line (p = .03, Chi square test)." (PMID 21731718, 2011). "Circulating tumour cell enrichment by CellSearch is based on the expression of the epithelial-lineage marker EpCAM (epithelial cell adhesion molecule)." (PMID 21829190, 2011). "Epithelial cell adhesion molecule (EpCAM) has been used as surrogate marker for the quantification of circulating tumour cells (CTC)." (PMID 21281486, 2011). "We previously investigated the presence of disseminated tumour cells in BM (DTC) in 316 patients with assumed CRC using immunomagnetic selection (IMS) with the anti-EpCAM antibody MOC31." (PMID 21448171, 2011). "According to a conflicting study, CD133 expression in human colon is not restricted to the stem cells but ubiquitous in differentiated colonic epithelium as well as tumor cells expressing epithelial cell adhesion molecule (EpCAM)." (PMID 24212669, 2011). "Catumaxomab (anti-EpCAM and anti-CD3) is a trifunctional monoclonal antibody with two different specificities, which binds simultaneously to the EpCAM on tumour cells and the CD3-antigen on T-cells." (PMID 22235224, 2011). "The EpCAM IMS-assay detected tumor cells with epithelial and mesenchymal-like characteristics, thus proving to be a more robust marker than pure epithelial derived biomarkers." (PMID 21816090, 2011). "We also had previously shown that using a positive enrichment strategy for cells expressing both EpCam and ErbB2 antigens resulted in the detection of higher levels of tumour marker gene expression than enriching for cells expressing just one of the antigens." (PMID 21587256, 2011). "The role of EpCAM in the development of cancer and in tumour progression is dependent on the tumour type as recently reviewed by us." (PMID 21694727, 2011). "Tumour cells have been detected and quantified in whole blood using the immunomagnetic EpCAM-based CellSearch® system (Johnson & Johnson)." (PMID 21281486, 2011). "The epithelial cell adhesion molecule (EpCAM) is overexpressed on carcinomas, and its downregulation inhibits the oncogenic potential of multiple tumour types." (PMID 21694727, 2011). "Percentages of EpCAM-expressing cells were slightly decreased in tumour compared with normal tissue, with a mean of 95.8 and 100% of positive cells, respectively (P<0.001)." (PMID 20606680, 2010). "MT110 recognizes EpCAM, a cell adhesion molecule expressed on TICs from diverse human carcinoma, which was recently shown to promote tumor growth through engagement of elements of the wnt pathway." (PMID 20976159, 2010).
tumor (continued). "Although the four major cell types were still present regardless of the tumor classification (Luminal (A or B), Her2, Basal), several tumor tissues contained a larger proportion of EpCAM-/CD49f+ Mesenchymal cells compared to reduction mammoplasty tissues." (PMID 20964822, 2010). "Over-expression of EpCAM reportedly correlates with biological aggressiveness and poor prognosis in CRC, possibly by promoting tumour immune evasion by strongly favouring T-helper cell type 2 (Th2) development that promotes growth of EpCAM-expressing tumors." (PMID 21339979, 2010). "EpCAM (also know as TACSTD1) is well characterized as a marker of epithelial tumor cells and anti-EpCAM antibodies have been widely used in the capture of CTCs." (PMID 20838621, 2010). "EpCAM+ tumor cells in the ascites fluid were significantly reduced after catumaxomab treatment to a median of zero after the last infusion (pooled population): 95/115 patients had a tumor-cell count of zero after the last infusion." (PMID 20473913, 2010). "We also evaluated the distribution of EpCAM at the mRNA level in patient tumor samples and found that while the majority of tumor types showed high EpCAM expression, we again noticed that a subset of samples from each tumor type had lower EpCAM expression." (PMID 20838621, 2010). "In this context, Gires and Baeuerle discussed the need to measure EpCAM expression levels in tumor cells and their impact on the outcome of a clinical trial." (PMID 21152431, 2010). "Loss of expression of CD166, CD44s, and EpCAM is rather linked to an aggressive tumour phenotype, particularly, to the presence of an infiltrating tumour margin that may implicate these proteins and their loss of membranous expression in events occurring at the invasive tumour front." (PMID 20606680, 2010). "Membranous EpCAM expression was evaluable in 1278 cases of which 1145 (89.6%) showed a diffuse staining in 100% of tumour cells." (PMID 20606680, 2010). "The authors also thank Dr. Michael Jäger for analyzing the ascites samples for EpCAM+ tumor cells, the freelance medical writers Mr." (PMID 20473913, 2010). "This high anti-tumor activity of MT110 will depend on the expression of the target antigen EpCAM and equally hit colorectal TICs and derived bulk tumor cells." (PMID 20976159, 2010). "Tumor cells were examined by flow cytometry for expression of estrogen receptor α, progesterone receptor, androgen receptor, her-2/neu, epithelial cell adhesion molecule, and CA125." (PMID 20356397, 2010). "Altogether, these studies suggest that diminished EpCAM expression is related to tumour invasiveness and progression." (PMID 20606680, 2010). "The automated system utilizes immunomagnetic nanoparticles directed against the epithelial cell adhesion molecule (EpCAM) to isolate and concentrate epithelial tumor cells." (PMID 20016752, 2010). "These tumour spheroid cells retain the expression of well-known cell surface markers, including CD133, CD166, CD44, and EpCAM, as well as other stem cell-associated proteins such as NES, BMI-1, and MSI-1." (PMID 20332776, 2010). "MT110 and related EpCAM-specific BiTE antibodies showed high anti-tumor activity in diverse animal models." (PMID 20976159, 2010). "These CD44+/CD24+/EpCAM+ cells presented self renewal capacity, tumor initiation and up-regulated of the Hedgehog signaling pathway." (PMID 24281178, 2010). "The emerging role of EpCAM as a signalling receptor and activator of the wnt pathway, and its expression on tumor-initiating cells, further add to its attractiveness as target for immunotherapy of cancer." (PMID 21044305, 2010). "Tumor cells were dissociated, incubated with anti-P-cadherin, -EpCAM, and -CD45 antibodies, and sorted by FACS." (PMID 20087418, 2010). "Under serum-free, stem cell selective culture conditions, ∼90% of these tumour spheroid cells were positive for CD133/EpCAM, as demonstrated by flow cytometry." (PMID 20332776, 2010).
tumor (continued). "Most of the current studies dedicated to the function of EpCAM have used in vitro systems, revealing a rather pleiotropic nature of EpCAM's roles during tumor progression and normal epithelial development." (PMID 19609345, 2009). "Immunomagnetic beads were coated with antibodies targeting two different proteins reported to be present on the surface of tumour cells of epithelial origin, BerEP4 which recognises the EpCam glycoprotein and EMA which recognises the MUC1 protein." (PMID 19961621, 2009). "Epithelial cell adhesion molecule was found to be highly elevated in pre-malignant hepatic tissues and was discussed as a marker for tumour progenitor cells." (PMID 19002182, 2008). "Taken together, EpCAM antibody treatment seems to make tumour cells recognisable for immune response in vivo, and the antineoplastic effects of the antibody require the immune response." (PMID 19002182, 2008). "The in vitro pro-proliferative effects of anti-EpCAM treatment shown in this study are surprising, as in vivo application of anti-EpCAM antibody resulted in tumour growth suppression." (PMID 19002182, 2008). "Some studies have also used a new CellSearch System technology that employs immunomagnetic separation of epithelial cells based upon expression of cytokeratins or EpCAM and visualization of the tumor cells by immunoflorescent microscopy." (PMID 18289390, 2008). "The genes like CK19, muc1, PSE and EpCAM that show significant background expression in normal samples, loose its accuracy in tumor cell detection when Ficoll density gradient cell separation methodology is used." (PMID 18289390, 2008). "This antigen is therefore explored in tumour diagnosis, and clinical trials have been initiated to examine EpCAM-based therapies." (PMID 19002182, 2008). "This seemingly contradicts a recent study that suggested EpCAM silencing leads to reduced invasive potential of tumour cells." (PMID 17325709, 2007). "Trifunctional antibodies (trAbs) with a dual specificity for EpCAM expressed on tumour cells and CD3 expressed on T cells represent an innovative immunotherapeutic approach to fight cancer." (PMID 17622246, 2007). "D Herlyn (Philadelphia, USA) reviewed progress on using EpCAM as a vaccine to elicit tumour-specific T-cell and humoral immune responses." (PMID 17211480, 2007). "Since then, there have been a plethora of therapeutic approaches guided by the idea of targeting tumour cells via EpCAM." (PMID 17622246, 2007). "A validated platform for detection and quantitation of circulating EpCAM+ tumour cells (CTC) has been established and is now being explored for therapy monitoring." (PMID 17211480, 2007). "This presents yet another paradox suggesting that, once neoplastic transformation has taken place, a reduced EpCAM expression is an indicator of a more aggressive tumour phenotype with increased invasion, metastasis and mortality." (PMID 17325709, 2007). "When comparing pairs of carcinomas and EpCAM-positive thyroid tissue from the same patients (n=26), a significant hyperglycosylation of EpCAM in tumours was observed in 80.7% of specimen." (PMID 17622246, 2007). "P McLaughlin (Groningen, the Netherlands) investigated the consequences of targeting monoclonal antibodies to normal and tumour tissue in a transgenic murine model expressing human EpCAM." (PMID 17211480, 2007). "EpCAM expression density varies at different stages of tumour growth suggesting that patient antigen positivity should be assessed before clinical use." (PMID 17325709, 2007). "The capacity of HO-3 or the therapeutic trAb catumaxomab to induce the killing of EpCAM-positive tumour cells by immune effector cells was compared in vitro." (PMID 17622246, 2007).
tumor (continued). "Biodistribution studies in EpCAM transgenic mice suggested preferential access of EpCAM-specific mAbs to tumour cells in spite of a background expression of EpCAM on healthy tissue." (PMID 17622246, 2007). "With specific inhibitors of EpCAM cleavage, a pharmacological means is given to interfere with EpCAM signalling in tumour cells." (PMID 17211480, 2007). "A rapid clearance of essentially all EpCAM-positive tumour cells in ascites fluid and an expansion of T-cell numbers were observed, which was followed by a retraction of immune cell counts." (PMID 17211480, 2007). "Taking this into account, mAbs such as HO-3 that are insensitive to the glycosylation status of EpCAM have an expanded potency to target a great variety of EpCAM-positive tumours." (PMID 17622246, 2007). "At least weak EpCAM expression in >10% of tumours was observed in 87 of 131 different tumour categories." (PMID 17325709, 2007). "Improved treatment results with the strongly binding mAb 323/A3 in a mouse xenograft tumour model speak in favour of the clinical development of high-affinity anti-EpCAM therapeutic antibodies." (PMID 17622246, 2007). "The proliferation of ras-transformed syngeneic tumour cells expressing human EpCAM was suppressed in vivo suggesting the potential of VV GA733-2 as a candidate vaccine for patients with CRC." (PMID 17325709, 2007). "Colonic (81%), gastric, pancreatic (78%) and lung carcinomas revealed a high proportion of strongly positive tumours, suggesting EpCAM is an attractive target for pan-carcinoma immunotherapy." (PMID 17325709, 2007). "The cytotoxic potential of PBMC was assessed by XTT staining after co-cultivation of PBMC and EpCAM-positive tumour targets for 3 days." (PMID 17622246, 2007). "In these patients staged as M0 (no metastasis), BR (biochemical PSA relapse), and M1 (established metastasis), EpCAM-positivity of bona fide tumour cells significantly increased with progression from M0 to BR, and further to M1 stages from 9 to 16–33%." (PMID 17211480, 2007). "Recently, antibodies against EpCAM such as Edrecolomab and Catumaxomab were developed, and clinical trials with these antibodies have been used in several types of neoplasia." (PMID 17125516, 2006). "The epithelial origin of the tumor cells was proven by morphological criteria including the presence of mucin within the cells and the expression of the cell adhesion molecules EpCAM and CEACAM1." (PMID 16536871, 2006). "Epithelial cell adhesion molecule frequency was lowest in pT4 tumours (77.8%), while all other subgroups showed Ep-CAM expression in more than 80% of tumours." (PMID 16404366, 2006). "By targeting CE2 to EpCAM, the enzyme should accumulate specifically in tumours and leakage into the circulation should be minimised." (PMID 15756257, 2005). "By immunomagnetic selection with HER2/neu and EpCAM as catcher antigens single disseminated tumor cells can be enriched from BM samples." (PMID 15771776, 2005). "Previous studies with monoclonal antibodies against the pan-carcinoma antigen, epithelial cell adhesion molecule (Ep-CAM), have shown tumour selectivity." (PMID 11875747, 2002). "We therefore constructed an intact bispecific antibody, BiUII (anti-CD3 × anti-EpCAM), that not only recognizes tumour cells and T lymphocytes with its two binding arms, but also binds and activates Fcγ-receptor positive accessory cells through its Fc-region." (PMID 10901380, 2000). "Furthermore, depletion/reconstitution experiments demonstrated that tumor‐derived EpCAM+ exosomes were responsible for transferring miR‐93‐5p into RBCs, since removal of these exosomes reduced loading and spike‐in restored it." (PMID 41159542, 2026). "Most tumor cell lines localized to the “population 1” gate, with the exception of CaSki cells, which were predominantly found in “population 2”—a gate defined as EpCAM positive based on isotype controls." (PMID 41154384, 2025).
tumor (continued). "Since the literature suggests that pituitary ACTH-secreting tumors may contain both EpCAM-positive tumor cells and CD44-positive tumor stromal fibroblast-like cells, we quantified the populations of EpCAM+ and CD44+ cells via flow cytometry analysis." (PMID 40002253, 2025). "Although the authors deemed the treatment safe, making any conclusions on its efficacy was challenging, partly because the clinical response was more strongly correlated with the tumor burden at the start of the study than with the actual treatment of EpCAM CAR-T cells." (PMID 40869256, 2025). "Notably, EpCAM exhibits high expression levels in various cancers, tumor-initiating cells, and circulating tumor cells, and is therefore considered a promising therapeutic target for cancer treatment." (PMID 41357552, 2025). "This system could elicit a strong anti-tumour response in vitro and in vivo against EpCAM- and mesothelin-expressing cells in a dose-dependent manner." (PMID 41465327, 2025). "Moreover, researchers have found EpCAM-positive tumor cells in peritoneal effusions from multiple types of epithelial cancers." (PMID 41275209, 2025). "Two anti-EpCAM sdAbs (aEP3D4 and aEP4G2) were evaluated for their anti-tumor effect in vivo and could inhibit tumor growth in a mouse tumor xenograft model." (PMID 40017594, 2025). "Several additional transcripts, including EpCAM, CK19, NANOG, PROM1, TERT, CDH5, FAM83A, and PTHLH, as well as high expression levels of BCL2, CD274 (PD-L1), CDH1, EPCAM, FGFR1, FN1, KRT18, MET, and MUC1, have been linked to reduced survival and aggressive tumor biology in NSCLC." (PMID 41373464, 2025). "Furthermore, EpCAM expression correlated with serum tumor markers such as CEA, which increases its importance in cancer detection and monitoring." (PMID 39941799, 2025). "In these immunodeficient mice, EpCAM-NIR-PIT resulted in slight tumour growth suppression compared to the control and AbPC intravenous injection-only groups, but there was no significant improvement in survival, likely due to the regrowth of residual cancer cells." (PMID 40792441, 2025). "EpCAM-based detection may be insufficient to capture the prognostic significance of highly tumor-specific CTCs." (PMID 40924249, 2025). "The CellSearch System enriches tumor cells using ferromagnetic beads coated with EpCAM antibodies." (PMID 40547026, 2025). "We used a biotin anti-EpCAM antibody and two different DNA templates, C1 and C2, to construct two kinds of antibody-DNA conjugates, allowing the two antibody-DNA conjugates to label the tumor exosomes." (PMID 39911266, 2025). "Moreover, according to the same study, unlike CD166, CD133, CD24, CD90, CD44s and ALDH1, the expression of EpCAM and ABCG5 within tumor buds is often associated with a poor prognosis." (PMID 40564019, 2025). "However EpCAM is a CSC marker that has also been demonstrated in circulating tumor cells (CTCs), and it is a marker that is correlated with tumor recurrence and metastasis." (PMID 40869256, 2025). "The APT-PEG-Au-MMNPs@ELC platform, incorporating gold nanoparticles, mesoporous silica, and EpCAM aptamers, enables pH-responsive drug release and tumor-specific targeting, effectively suppressing tumor growth in vitro and in vivo while reducing systemic toxicity." (PMID 41404421, 2025). "Notably, we successfully delineated tumour regions exhibiting differential EPCAM expression, aligning with the expert pathologist's assessment." (PMID 39810624, 2025). "EpCAM, a membrane protein, was clearly detectable in both tumor tissues and organoids." (PMID 41009433, 2025). "Therefore, strategies to modulate EpCAM within the tumor microenvironment must carefully balance therapeutic efficacy with safety." (PMID 39996844, 2025). "Instead of using EpCAM alone, the AdnaTest uses multiple tumor‐specific antibodies." (PMID 40437761, 2025).